SGK1 (serum/glucocorticoid regulated kinase 1)
Diseases named in the same sentence as SGK1 in open-access papers (continued):
Sharing a sentence is not in itself a finding about the gene and the disease.
non-small cell lung carcinoma (9 papers, 2012 to 2024). A group of at least three distinct histological types of lung cancer, including non-small cell squamous cell carcinoma, adenocarcinoma, and large cell carcinoma. "Sgk1 is well known to activate beta-catenin/T cell factor signaling in human non-small cell lung cancer, and to be associated with tumor cell invasion and migration." (PMID 32106831, 2020). "In 224 patient samples and 103 matched adjacent of non-small cell lung cancer samples, it was first established that expression of SGK1 mRNA in cancerous tissues was way higher compared to the adjacent non-cancerous tissues (p < 0.001)." (PMID 35625991, 2022). "SGK1, identified in our study as a target gene of both STAT5A and STAT5B, has also been implicated in the pathophysiology of non-small-cell lung cancer and adrenocortical tumors in humans, although this has not been reported in rodents." (PMID 24497979, 2014).
autoimmune disease (8 papers, 2014 to 2024). A disorder resulting from loss of function or tissue destruction of an organ or multiple organs, arising from humoral or cellular immune responses of the individual to their own tissue constituents. "SGK1 has also recently been implicated in the loss of Treg in human autoimmune diseases where increases in the PRDM1-short isoform drive SGK1 expression." (PMID 39366761, 2024). "Recent studies have shown that SGK1 regulates the balance between Th17 and Treg cells, and that deficiency of SGK1 can correct autoimmune diseases caused by Th17/Treg ratio imbalance." (PMID 35222400, 2022). "The data presented in these manuscripts clearly indicate that high intake of sodium potentiates pathogenic Th17 cell generation in in vitro and in vivo systems in an SGK1-dependent manner and, therefore, has the potential of increasing the risk of promoting autoimmune diseases." (PMID 24688790, 2014). "Others have detected NaCl-induced augmentation of proinflammatory Th17 phenotype in an autoimmune disease setup, mediated by SGK1 and NFAT524." (PMID 28331179, 2017). "SGK1 is also regulated by PI3K phosphorylation, which promotes Th17 cell differentiation, hinders Treg cell formation, and accelerates autoimmune disease development." (PMID 35222400, 2022). "In several studies using autoimmune disease models, HSD increased the Th17 immune response via the serum/glucocorticoid-regulated kinase (SGK1) differentiation of Th17 cells." (PMID 33126615, 2020). "Most recently, it was found that high-salt conditions activate the p38/MAPK pathway involving NFAT5 and SGK1 during cytokine-induced TH17 cell polarization, suggesting that dietary salt may influence autoimmune disease in humans through T-cell-induced production of IL-17." (PMID 25309574, 2014).
colitis (8 papers, 2017 to 2025). Inflammation of the colon. "A significant increase in plasma aldosterone production, a higher colon MR protein level and a higher colon SGK1 protein level were observed in male mice with chronic DSS-induced colitis." (PMID 40634309, 2025). "Based on the hypothesis that targeting MR could be useful for inhibiting intestinal fibrosis, we first assessed the plasma level of the MR ligand, aldosterone, the level of colon MR expression, and the aldosterone-MR target, SGK1 in the chronic DSS colitis-induced intestinal fibrosis model." (PMID 40634309, 2025). "High salt diet (HSD) exacerbates colitis in the Il10–/– colitis model by activating p38 MAPK and SGK1 in dendritic cells." (PMID 40121360, 2025). "Mice treated with SCH experienced significant weight gain, effectively alleviating the severity of colitis, and decreasing the levels of inflammatory factors such as TNF-α, IL-1β, IL-18, IL-6, and other related proteins (NLRP3, Caspase-1, SGK1) in UC mice." (PMID 37674245, 2023). "We also examined SGK1, CEP55, ACSL1, OLFM4, DPP10, and MGP expression in the colon tissues of dextran sodium sulfate‐induced colitis mice." (PMID 34939750, 2022). "To further confirm the differential expression of these candidate genes between ulcerative colitis and normal groups, we determined the mRNA expression of SGK1, CEP55, ACSL1, OLFM4, MGP, and DPP10 in colon tissues of DSS‐induced colitis mice." (PMID 34939750, 2022). "In a mouse model of colitis, mice receiving a high salt diet developed more severe colitis that was abrogated by a pharmacologic agent that controlled p38/MAPK, and thus SGK1." (PMID 29740348, 2018). "In addition, we also examined the expression of SGK1, CEP55, ACSL1, OLFM4, DPP10, and MGP in the colon tissues of DSS‐induced colitis mice." (PMID 34939750, 2022). "In addition, we also examined the expression of SGK1, CEP55, ACSL1, OLFM4, DPP10, and MGP in the colon tissues of dextran sulfate sodium‐induced colitis mice." (PMID 34939750, 2022). "In mice fed with high-salt diet, Tregs secreted more IFN-γ and failed to control colitis and xenogeneic GvHD, which was dependent on SGK1 signaling." (PMID 32153577, 2020). "Of note, consumption of diets containing high concentrations of other salts such as potassium chloride also exacerbated DSS-induced colitis suggesting that sodium chloride and SGK1 activation may not be the only triggers of inflammation by HSDs." (PMID 29379505, 2017). "Of note, administration of diets rich in other salts such as magnesium and potassium chloride (data not shown) also resulted in worsening of DSS-induced colitis suggesting that pathways different from SGK1 may also lead to gut inflammation." (PMID 29379505, 2017).
diabetic nephropathy (8 papers, 2008 to 2025). "For instance, SGLT2 knockdown has been shown to restore the Th17/Treg balance and attenuate diabetic nephropathy in db/db mice by regulating SGK1 via sodium signaling." (PMID 41030847, 2025). "Next, we explored the expression level of SGK1 in the plasma samples of healthy people (NC = 25) and diabetic nephropathy patients (DN = 22)." (PMID 37079269, 2023). "Overall, our study highlighted the critical role of circCOL1A2/miR-424-5p/SGK1 axis in modulating HG-induced diabetic nephropathy, suggesting that targeting circCOL1A2 may be a potential intervention strategy for DN management." (PMID 37079269, 2023). "Hence, our results demonstrated that the circCOL1A2 mediates HG-exposed pyroptosis and oxidative stress through modulating miR-424-5p/SGK1 axis in diabetic nephropathy, indicating that silencing circCOL1A2 is a potential intervention strategy for DN management." (PMID 37079269, 2023). "SGK1 may also play a role in the development of other complications, such as diabetic nephropathy." (PMID 33003561, 2020).
ovarian carcinoma (8 papers, 2014 to 2022). A malignant neoplasm originating from the surface ovarian epithelium. "SGK1 is associated with Akt and phosphoinositide 3-kinase inhibitor and paclitaxel resistance in breast and ovarian cancer cells." (PMID 33406639, 2021). "SGK1 and another top upregulated DEG, DUSP1, have both been implicated in chemoresistance and apoptosis inhibition in ovarian cancer, with our own research showing that a dual inhibitor of DUSP1 and DUSP6 reversed chemoresistance in ovarian cancer cells." (PMID 36131935, 2022). "However, in a preclinical model of ovarian cancer, the SGK1 inhibitor SI113 counteracted the development of paclitaxel resistance and restored drug sensitivity." (PMID 33542904, 2020). "Secondly, WNT9A, PRKCB, SGK1, and DUSP6 have been shown to promote or inhibit the development of ovarian cancer." (PMID 32331314, 2020). "Drawing together these two anti-apoptotic mechanisms, and to confirm the effect of GCs on the regulation of anti-apoptotic genes, the expression of SGK-1 and MKP-1 was evaluated in a clinical setting in ovarian cancer patients." (PMID 35582576, 2019). "In ovarian carcinoma, in vitro assays showed that in glucocorticoid receptor (GR)-positive HeyA8 and SKOV3 cells, dexamethasone (100 nM) treatment upregulated the pro-survival genes SGK1, and MKP1/DUSP1 and inhibited carboplatin/gemcitabine-induced cell death." (PMID 33542904, 2020). "Thus, under the experimental conditions chosen, Akt1 rather than SGK1 contributes to the therapy resistance of A2780cis ovary carcinoma cells." (PMID 25015419, 2014).
renal fibrosis (8 papers, 2014 to 2025). A final common manifestation of a wide variety of chronic kidney diseases characterized by glomerulosclerosis and tubulointerstitial fibrosis. "The genetic ablation of SGK1 blunts proteinuria and renal fibrosis in response to elevated mineralocorticoid action." (PMID 38673987, 2024). "The researchers demonstrated that the overexpression of SGK1 had been observed in a variety of fibrosis diseases, including pulmonary fibrosis, renal fibrosis and hypertensive cardiac fibrosis." (PMID 38250161, 2024). "Thus, the FOSL2/SGK1 axis may be a novel target for molecular-targeted therapies for renal fibrosis." (PMID 37662889, 2023). "Thus, the FOSL2/SGK1 axis may serve as a potential therapeutic target for inhibiting the development of renal fibrosis." (PMID 37662889, 2023). "Therefore, the FOSL2/SGK1 profibrotic axis may be a promising biomarker and therapeutic target for renal fibrosis." (PMID 37662889, 2023). "SGK1 also stimulates the secretion of TGF-β and accelerates renal fibrosis." (PMID 40427579, 2025). "Notably, we also found that FOSL2 knockdown repressed the activation of SGK1 transcription, suggesting that the FOSL2/SGK1 axis plays an important role in TGF-β1–mediated pathological effects on renal fibrosis." (PMID 37662889, 2023). "Bioinformatics analysis revealed that serum/glucocorticoid regulated kinase 1 (SGK1) may be regulated by FOSL2 and involved in renal fibrosis." (PMID 37662889, 2023). "FOSL2 plays an essential role in promoting renal fibrosis in an SGK1-dependent manner, and targeting the FOSL2/SGK1 signaling axis may offer a potential strategy for the treatment of renal fibrosis." (PMID 37662889, 2023). "Recent studies suggest that SGK1 mediates AngII-induced sodium reabsorption via sodium-hydrogen exchanger-3 (NHE3) expression and Na+ reabsorption in proximal tubular cells, and renal fibrosis by stimulating connective tissue growth factor (CTGF) expression in human kidney fibroblasts." (PMID 30524295, 2018).
heart failure (7 papers, 2016 to 2023). Inability of the heart to pump blood at an adequate rate to meet tissue metabolic requirements. "It was shown that cardiac SGK1 is activated in human and murine heart failure and that cardiac-specific activation of SGK1 in mice increased mortality, cardiac dysfunction, and ventricular arrhythmias." (PMID 37160311, 2023). "SGK1 has been shown to promote cardiomyocyte survival while inhibiting hypertrophy, whereas SGK1 chronic activation during heart failure is detrimental." (PMID 30705773, 2019). "By increasing Na+ entry and subsequently decreasing the chemical Na+ gradient through a NHE1-mediated pathway, SGK1 contributes to myocardial remodeling, cardiac hypertrophy and progression to heart failure." (PMID 27517916, 2016). "Stimulated by dexamethasone, SGK1 would participate in the development of heart failure and other cardiac pathophysiology by activating cardiac NHE1." (PMID 27517916, 2016). "Notably, SGK1 has been shown to contribute to cardiac remodeling and fibrosis, and development of heart failure." (PMID 31632443, 2019). "In addition, it has been reported that SGK1 plays a critical role in heart failure in transverse aortic constriction animal model." (PMID 30524295, 2018).
glioma (6 papers, 2016 to 2025). A benign or malignant brain and spinal cord tumor that arises from glial cells (astrocytes, oligodendrocytes, ependymal cells). "It was also demonstrated that dexamethasone (DEX), a steroid administered as standard of care in glioma treatment, induced SGK1 transcription resulting in increased phosphorylation of NDRG1 at T346." (PMID 40378957, 2025). "In addition, NDRG1 is affected by not only the tumor microenvironment but also glioma treatments such as radiation, chemotherapeutic agents, and steroids, and its pathway is the mechanistic target of the rapamycin C2 (mTORC2)/SGK1 pathway." (PMID 35448004, 2022). "The pharmacological inhibition of SGK1 using the compound, EMD638683, prevented the NDRG1-mediated protection of glioma from TMZ." (PMID 40378957, 2025). "Activation of mTORC2 and thus SGK1-phosphorylated NDRG1 is increased in temozolomide resistant glioma cell lines and NDRG1 expression is elevated in tissues specimens from glioma patients, suggesting that this is mechanistically important for MGMT-conferred resistance to alkylating therapeutics." (PMID 29301334, 2018). "In the present work, in a cohort of GBM patients, compared to non-tumor controls, we found that SGK1 expression correlated with high-grade glial tumors." (PMID 26908461, 2016).
Infertility (6 papers, 2008 to 2023). "Dysregulation of SGK1 expression has been found in unexplained infertility and recurrent pregnancy loss in humans which was functionally characterized in mouse models." (PMID 31752681, 2019). "SGK1, is a kinase participated in epithelial ion transport and cell survival, is up-regulated in unexplained infertility, most notably in the intraluminal epithelium, but down-regulated in the endometrium of women with recurrent abortion RPL." (PMID 36967990, 2023). "This biological role of SGK1 in the endometrium has important bearings on implantation because of the frequency of infertility in women with endometriosis." (PMID 33195190, 2020). "More precise understanding of the role of SGK1 in reproductive disorders mainly in infertility and miscarriage will provide potential promising opportunities for clinical intervention." (PMID 33195190, 2020). "Using a cDNA microarray, a previous study identified SGK1 as a gene aberrantly expressed specifically in luminal epithelia during the midsecretory receptive phase of the cycle in infertile women." (PMID 27517916, 2016). "For example, SGK-1 is of interest given its noted upregulation in the endometrium of women with unexplained infertility suggesting that this kinase is important for implantation and maintenance of early pregnancy." (PMID 18461179, 2008). "Aberrant regulation of SGK1 and ENaC in uterine epithelium could contribute to the pathogenesis of unexplained infertility in humans and mice." (PMID 32826848, 2020). "The primary evidence to imply the role of SGK1 in endometrial function and fertility arose from a microarray screening experiment of mid luteal (LH +5 to +10) endometrial biopsies obtained from both fertile (control) and infertile women." (PMID 33195190, 2020).
Insulin resistance (6 papers, 2016 to 2023). Increased resistance towards insulin, that is, diminished effectiveness of insulin in reducing blood glucose levels. "Clinical studies also implicated SGK1 activity in adipose tissue inflammation and insulin resistance." (PMID 34956089, 2021). "Furthermore, elevated PKC and mTORC2 activities, along with decreased SGK1 activity, have recently been associated with insulin resistance in mammalian cells." (PMID 26935949, 2016). "In models of metabolic syndrome, SGK1 signaling in hepatocytes and adipocytes has been shown to exacerbate insulin resistance." (PMID 35998035, 2022). "In our previous study, we found that phosphorylation of SGK1 in subcutaneous fat correlates with insulin resistance, T2DM, and impaired incretin profile." (PMID 34956089, 2021). "In vitro studies suggested that active SGK1 stimulates adipogenesis and insulin resistance." (PMID 34956089, 2021). "However, as we discuss above, omental fat can have more critical roles in developing insulin resistance and this study aims to analyze the insulin- and mTORC2-dependent signaling downstream SGK1 in the omental fat depot, which can be critical to metabolic diseases." (PMID 34956089, 2021). "Therefore, PKC and elevated SGK1 Thr5 phosphorylation may contribute to insulin resistance through control of mTORC2 and SGK1 activities." (PMID 26935949, 2016). "Additional studies are needed to further elucidate the potential role of mTOR/SGK1 and INS docking proteins INS receptor substrates 1 and 2 as mediators of the efficacy of SIT on insulin resistance." (PMID 30116740, 2018).
ischemia (6 papers, 2011 to 2024). A hypoperfusion of the BLOOD through an organ or tissue caused by a PATHOLOGIC CONSTRICTION or obstruction of its BLOOD VESSELS, or an absence of BLOOD CIRCULATION. "Oxidative stress and serum and glucocorticoid-induced Kinase 1 gene (SGK1) perform a central role in the consequences of ischemia in the heart." (PMID 36865044, 2023). "Inhibition of SGK1 by the SGK1 inhibitor GSK650394 has been found to reduce infarct size and blood-brain barrier disruption in ischemia-reperfusion injury during the early phase of cerebral ischemia, thereby protecting brain function." (PMID 39737082, 2024).
Myocardial fibrosis (6 papers, 2017 to 2025). "Specifically, we observed improvement in diastolic function, myocardial fibrosis, cardiomyocyte hypertrophy and ultrastructure of inter myofibrillar mitochondria that were associated with a significant improvement in glycemia, as well as improvement in myocardial expression of SGK1 and ENaC." (PMID 28086951, 2017). "Dapagliflozin inhibited myocardial fibrosis via inhibition of SGK1 and epithelial sodium channel (ENaC) protein, which was observed both in myocardial tissue and H9C2 cells." (PMID 36068525, 2022). "The dapagliflozin-treated group showed attenuation of myocardial fibrosis with reduction of SGK1/ENaC/NHE1 proteins in myocardial tissue and H2C2 cells." (PMID 36068525, 2022). "Serum-glucocorticoid regulated kinase 1 (SGK1) is involved in angiotensin-II induced myocardial fibrosis." (PMID 36320147, 2022). "Importantly, LIGHT primes macrophage polarisation toward the M2 phenotype by activating the PI3Kγ/SGK1 pathway, leading to myocardial fibrosis and AF vulnerability." (PMID 37580750, 2023). "In DbC, myocardial fibrosis was accompanied by increased expression of profibrotic/prohypertrophic proteins, serum/glucocorticoid regulated kinase 1 (SGK1) and the epithelial sodium channel (ENaC), and the development of these abnormalities were reduced with EMPA." (PMID 28086951, 2017). "In this study, we revealed a new and independent mechanism in LIGHT-induced myocardial fibrosis, wherein LIGHT enhancing the PI3K pathway in cardiac macrophages and upregulated SGK1 levels, thus enhanced M2 macrophage polarisation." (PMID 37580750, 2023).